SOD2 (superoxide dismutase 2)
Diseases named in the same sentence as SOD2 in open-access papers (continued):
Sharing a sentence is not in itself a finding about the gene and the disease.
diabetes (continued). "In conclusion, increased expression of PRR localized in renal mitochondria and diabetic kidney induced mitochondria dysfunction, and enhanced renal apoptosis and fibrosis in diabetes by upregulation of mitochondria NOX4/SOD2/UCP2 signaling pathway." (PMID 31406124, 2019). "Several studies have investigated the relationship between SOD2 genotypes and diabetes’ complications." (PMID 29682485, 2017). "This increase was significantly reversed by APS treatment in hearts with diabetes and/or with partial SOD2 depletion." (PMID 28700033, 2017). "Compared with that in C57BJ/6J control hearts, the generation of H2O2 nearly doubled in myocytes from hearts with diabetes and/or with partial SOD2 depletion." (PMID 28700033, 2017). "A study that investigated the association between SOD2 and kidney diseases has shown a positive association between SOD2 Ala/Val and Val/Val genotypes and both CVD and diabetes." (PMID 29682485, 2017). "Our data revealed that the percentages of both nitrotyrosine-labeled myocytes and 8-OH-dG labeled myocytes increased by 3-fold to 4-fold in hearts with diabetes and/or with partial SOD2 depletion, compared with that in C57BJ/6J control hearts." (PMID 28700033, 2017). "Both SOD1 and SOD2 single nucleotide polymorphisms (SNPs) are found to be associated with 2- to 3-fold higher risk of developing diabetic nephropathy in type 1 and 2 diabetes mellitus (DM) patients." (PMID 26881045, 2016). "In the context of diabetes, increased levels of SOD2 mRNA have been found in skeletal muscle of patients with T2DM." (PMID 25279756, 2014). "Collectively, the data suggest that hyperglycemia-induced mitochondrial oxidative stress is a major trigger of diabetes-related neuronal injury that can be ameliorated by increasing SOD2 activity." (PMID 20976160, 2010). "Cat, Sod1, Sod2, Prkca, and Nos1 expression levels were decreased, while Ncf1, Xdh, and Cyba expression levels were increased in diabetes." (PMID 20979611, 2010). "Previous studies have shown that SOD2 -9T/C and MTHFR 677 C/T polymorphisms were associated with diabetes, cancer and cardiovascular diseases in other populations." (PMID 20003469, 2009). "Since oxidative stress plays a crucial role in pancreatic β-cell dysfunction and directly contributes to the development of clinical diabetes, upregulating antioxidant enzymes like SOD2 in the β-cell may provide a novel method of diabetes treatment." (PMID 41033431, 2026). "Additionally, several proteins were linked to metabolic disorders such as obesity, diabetes, and hyperuricemia, including AGRP, LEP, SORT1 and SOD2." (PMID 40242450, 2025). "Similarly, although MRRP1 and LncCytB interaction was decreased in the WT-D group, Sod2 overexpression prevented this diabetes-induced decrease, and the values for the WT-N, Sod-N and Sod-D groups were not significantly different from each other (p > 0.05)." (PMID 39200102, 2024). "Transgenic overexpression of SOD2 in the mouse retina prevents diabetes-induced oxidative stress." (PMID 37627644, 2023). "In diabetes, ROS production in the retina is significantly increased and further exacerbated by the collapse of antioxidant defensive system, including superoxide dismutase (SOD2) and glutathione peroxidase (GPX4)." (PMID 36092160, 2022). "We evaluated the potential effect of HSCT with increased Sod2 on maternal diabetes–mediated ALB." (PMID 35220596, 2022). "Similarly, one study discovered that SOD2 is a mitochondrial enzyme with increased mRNA expression in patients with type 2 diabetes mellitus and those with Parkinson's disease." (PMID 35481271, 2022). "Antioxidant enzymes SOD1/SODC and SOD2/SODM were also increased by diabetes in wild‐type mice." (PMID 34277994, 2021). "Furthermore, diabetes affected the SOD2 gene by increasing significantly its expression in the liver, compared to the control group (p < 0.01).However, crocin administration did not alter this effect." (PMID 32161725, 2020).
diabetes (continued). "Additionally, ERβ overexpression in the amygdala significantly restores prenatal progestin exposure-induced ALB, and maternal diabetes-induced autistic offspring show significant SOD2 suppression in the amygdala as well." (PMID 32327976, 2020). "To investigate the mechanisms of MSCs against diabetes-induced lung fibrosis, we hypothesized that the capability of MSCs might mainly result from upregulating the Sirt3/SOD2 signaling pathway." (PMID 32089781, 2020). "In addition, we measured the maternal diabetes-induced epigenetic changes on the SOD2 promoter in isolated amygdala neurons." (PMID 31685635, 2019). "An increase in SOD2 expression could be beneficial by decreasing reactive oxygen species production as it was described in other diseases such as diabetes." (PMID 29116107, 2017). "Furthermore, diabetes and/or oxidative stress by partial SOD2 depletion increased myocytes necrosis by 4- to 6-fold in diabetic mice, SOD2+/- mice and diabetic SOD2+/- mice, compared with that from C57BJ/6J control mice." (PMID 28700033, 2017). "Furthermore, the promoter and enhancer regions of superoxide dismutase-2 (SOD-2) change in diabetes, and histone lysine acylation and methylation in monocytes at inflammation- and diabetes-related gene loci can be induced by hyperglycemia." (PMID 28265339, 2017). "The results of the present study suggest that APS might have a beneficial effect on the apoptosis and necrosis of cardiomyocytes with either diabetes and/or oxidative stress by partial SOD2 depletion." (PMID 28700033, 2017). "In addition, APS treatment also reversed the increase in myocyte necrosis of the left ventricle with diabetes and/or partial SOD2 depletion." (PMID 28700033, 2017). "Regression analysis showed that TT genotype of SOD2 Val16Ala conferred significantly lower ESRD risk among patients without diabetes (odds ratio 0.699; p = 0.018)." (PMID 26881045, 2016). "Furthermore, the integrated optical density (IOD) of SOD2 and uPA stainings is higher in the tumor tissues of pancreatic cancer patients with diabetes compared with pancreatic cancer patients with euglycemia." (PMID 26439801, 2015). "Another relevant biomarker of MDF, SOD-2 expression, was reported to be increased in gastric cancer and hepatocellular carcinoma; SOD-2 activity was found increased in atherosclerosis, type 2 diabetes mellitus, and upregulated SOD-2 transcripts in Hutchinson-Gilford syndrome." (PMID 24876913, 2014). "Diabetic kidneys had increased transcript and membrane-bound protein levels of Nox4, the renal-specific generator of cytosolic reactive oxygen species (ROS) and reduced expression of SOD2, UCP2, GPX3, NQO1, and CAT." (PMID 23149823, 2013). "Furthermore, overexpression of SOD2 significantly prevented the development of retinopathy in mice by preventing retina from diabetes-induced oxidative damage." (PMID 20976160, 2010). "Other studies suggest that Ala16Val SNP of SOD2 gene is not related to pathogenesis of diabetes but is associated with microangiopathy expressed as microalbuminuria or macular edema in patients with T2DM." (PMID 18423055, 2008). "Better diabetes control was found in patients with CC than with TT genotype of SOD2 gene." (PMID 18423055, 2008). "Association of the SOD1, SOD2 and CAT polymorphism, BMI, age, duration of diabetes, sex, type of diabetes and SOD activity as independent variables with the presence of microangiopathy or macroangiopathy as dependent variables was performed using a logistic regression model." (PMID 18423055, 2008). "The reduction in SOD2 may underline the finding that mitochondria are the main site of producing superoxide in diabetes, Since SOD2 plays a central role in metabolizing O2.− in mitochondria the maintained level of SOD1 may prevent O2.− overproduction in diabetic conditions." (PMID 29870994, 2018).
diabetes (continued). "Moreover, dermal expression of mitochondrial superoxide dismutase (SOD2) expression in the lower limbs was augmented by ≈60 % and correlated with increasing diabetes duration, cardiac sympathetic predominance, and diminished vagal activity, while subepidermal endothelial cell area was not altered." (PMID 27053136, 2016). "Thus, SOD2/H2O2/MAPK axis may represent a promising therapeutic target for pancreatic cancer patients combined with diabetes mellitus." (PMID 26439801, 2015). "Research also found that tea polyphenols lowered ROS in diabetic oocytes while boosting the expression of Sod1, Sod2 and other antioxidant genes, thereby mitigating the detrimental impact of STZ-induced diabetes on oocyte quality." (PMID 40110863, 2025). "Studies in humans and experimental models indicate that superoxide dismutase 2 (SOD 2), glutathione peroxidase (GPx), and catalase activities in the mitochondria decrease due to hyperglycemia in diabetes." (PMID 38792935, 2024). "On the other hand, HSCT operation and the manipulation of Sod2 expression diminish maternal diabetes–mediated systematic oxidative stress (e.g., increased GSH/GSSG ratio), subsequently reversing maternal diabetes–mediated GI symptoms and ASD development." (PMID 35220596, 2022). "RT-PCR analysis of blood RNA obtained from NS-3 treated people with T2DM for 24-weeks resulted down-regulation of gene expression in diabetes biomarkers (IRS-1, SOD-2, GCKR, IGFPB-2) compared to pre-dose values." (PMID 36540866, 2022). "The results showed that maternal diabetes (STZ/WT) significantly decreased the expression of RORA, CYP19A1, and SOD2 compared to the control (CTL/WT) group, and prenatal RORA deficiency mimicked the effect of maternal diabetes." (PMID 35027651, 2022). "We first evaluated gene expression from IEC, and the results showed that maternal diabetes (STZ/WT) significantly decreased mRNA levels of RORA, CYP19A1 and SOD2, respectively, compared to the CTL/WT group." (PMID 35164690, 2022). "We first evaluated gene expression in the amygdala, including mRNA and protein levels, and found that maternal diabetes (STZ/P-VEH) significantly decreased the expression of RORA, CYP19A1, and SOD2 compared to the control (CTL/WT) group." (PMID 35027651, 2022). "Concerning the potential role of LPIN1 rs13412852, KLF6 rs3750861, SOD2 rs4880, TM6SF2 rs58542926, and ZNF624 rs12603226 SNPs in glycemic control of the patients with diabetes, data are also limited." (PMID 34746177, 2021). "In addition to TXNIP and the Trx/TrxR redox system, other ROS generating systems (NADPH oxidase and Xanthene oxidase) and anti-oxidants (GSH, SOD1, and SOD2) may also be involved in dysregulation of the mitochondrial–lysosomal axis in diabetes and under glucolipotoxicity." (PMID 34940029, 2021). "Our results showed that STZ-induced diabetes induces histone methylation on the ERβ promoter and subsequently suppresses ERβ and its target genes, including NRF1 and SOD2, in HSCs." (PMID 33654697, 2021). "Diabetes-induced HDAC2 upregulation diminishes the acetylation of histone H3K9 and H3K27, therefore, reduces SOD2 expression." (PMID 33996829, 2021). "Bone marrow transplantation of normal HSC to maternal diabetes-induced autistic offspring transferred epigenetic modifications to PBMC and significantly reversed SOD2 suppression and oxidative stress and elevated inflammatory cytokine levels." (PMID 33101089, 2020). "SOD2 overexpression in the maternal diabetes group (STZ/↑SOD2) partly restored this effect, while SOD2 knockdown in control offspring (CTL/shSOD2) partly mimicked it." (PMID 31685635, 2019). "Again, SOD2 expression (STZ/↑SOD2 group) completely restored, and SOD2 knockdown (CTL/shSOD2 group) mimicked, the effect of diabetes." (PMID 31685635, 2019). "Consecutively, MCS-D-EPCs showed increased Sod-2 expression, indicating that the presence of Klotho in MCS induces Sod-2 expression in D-EPCs leading to resistance to diabetes-induced oxidative damage." (PMID 30153276, 2018).
diabetes (continued). "Quantitative real time PCR results demonstrated that gene expression levels of main antioxidant enzymes SOD-1, SOD-2 and detoxification enzymes GST-Mu and GST-Pi were suppressed with diabetes." (PMID 25905778, 2015). "In adipose tissue, we found not only a number of known cancer-related genes, like SOD2 or AMACR, but also diabetes- and obesity-related genes, like MTHFR or ADIPOR2." (PMID 23889843, 2013). "Western blot analysis revealed decreased levels of SOD2 and PGC-1α and increased levels of Ac-SOD2 in db/db mice, while PET treatment reversed these trends, which suggested that PET could improve mitochondrial function in diabetes." (PMID 41181708, 2025). "The role of hsa-miR-503 in pathomechanism of diabetes complications depends on mitochondrial activity (DHFR), cell cycle control (CCNE2), cell protection (SOD2), podocyte migration (ANLN), inflammatory process (IL10, EFE2, VEGFA) and fibrosis (COL1A1), showing its contribution to CKD development." (PMID 36859746, 2023). "The results showed that maternal diabetes (STZ/VEH) significantly decreased the mRNA levels of RORA, CYP19A1 and SOD2 (P < 0.0001) compared to the CTL/VEH group; MnTBAP treatment (STZ/MnTBAP) completely, while STZ/SR1078 treatment partly (P < 0.01), reversed this effect." (PMID 35164690, 2022). "This further confirmed that HSCT with increased Sod2 expression did not affect maternal diabetes–mediated SOD2 suppression in IECs." (PMID 35220596, 2022). "Furthermore, we evaluated SOD2 activity; again, STZ‐HSCT/STZ/↑Sod2 treatment partly reversed, while CTL‐HSCT/CTL/shSod2 treatment mimicked, maternal diabetes–mediated Sod2 suppression." (PMID 35220596, 2022). "Diabetes induced downregulation of both SOD-1 and SOD-2 protein." (PMID 33923282, 2021). "The results showed that STZ/VEH treatment decreased mRNA expression of ERβ, NRF1 and SOD2 to 68%, 39% and 42%, respectively, compared to the CTL/VEH group, while both RSV (STZ/RSV) and PTE (STZ/PTE) treatment completely restored diabetes-induced (STZ/VEH) gene suppression." (PMID 33654697, 2021). "The cardiac expression of SOD2 also had a similar pattern, although to a less extent (significantly higher only in 36-week male OVE26 mice), ratifying the sex difference in oxidative stress response during the course of diabetes progression." (PMID 32509150, 2020). "Furthermore, we had also detected the oxidative stress level (upstream of ASK1-JNK1/2 signaling) and found that diabetes significantly inhibits SOD1 and SOD2 expressions and elevates NOX2 level in the hippocampus." (PMID 32766246, 2020). "No variations of SOD1 and SOD2 levels were found but diabetes led to a rise of SOD2 acetylation in DIAB and DIAB+GTE groups (+44% and +35%, respectively, p < 0.001)." (PMID 31690052, 2019). "After APS treatment, H2O2 formation did not significantly increase in myocytes from hearts with diabetes and/or with partial SOD2 depletion." (PMID 28700033, 2017). "Among molecular parameters, HA is modulated by diabetic CAD-related alterations while SOD2 and LXRα are found to be more associated with CAD rather than to diabetes." (PMID 28871240, 2017). "In the present study, it was found that diabetes inhibited SOD activity in control hearts to the extent of the inhibition of SOD activity in hearts by partial SOD2 depletion alone, suggesting that diabetes had a negative effect on SOD activity in myocytes." (PMID 28700033, 2017). "The presented findings show that the genotype distribution of the SOD1 and SOD2 in patients with diabetes mellitus can differed from nondiabetic individuals." (PMID 18423055, 2008). "Moreover, in the hypothalamus, SOD2 mRNA levels did not significantly change in maternal diabetes (STZ/WT) group, while they were significantly decreased in the prenatal RORA deficiency (RORA−/−) group compared to the control (CTL/WT) group." (PMID 35027651, 2022).
diabetes (continued). "In addition, mRNA levels of sod2, which is an important mitochondrial enzyme against oxidative stress, did not change significantly with diabetes and/or resveratrol." (PMID 30602713, 2018). "Given that SOD2 is regulated by a plethora of antioxidant gene promoters, including NFEL2L (also known as NRF2), which is downregulated in several diabetes models, we attempted to verify whether NRF2 could modulate SOD2 under miR-21 induction during OG and HG exposures." (PMID 30037352, 2018). "Furthermore, APS treatment inhibited cardiac H2O2 formation, reduced cardiac oxidative stress/damage, and increased SOD activity in cardiomyocytes from heterozygous SOD2+/- knockout hearts with or without diabetes." (PMID 28700033, 2017). "However, diabetes demethylates H3K4, and the recruitment of LSD1 at Sod2 promoter is increased." (PMID 24286082, 2013). "Diabetes induction altered neither the gene expressions of catalase mRNA level, a cytosolic H2O2 scavenger, nor SOD2, a mitochondrial superoxide detoxifier." (PMID 31690052, 2019). "The levels of SOD1, SOD2, and SOD3 in the three groups with diabetes were not significantly changed." (PMID 27830142, 2016).